TNF (tumor necrosis factor)
Diseases named in the same sentence as TNF in open-access papers (continued):
Sharing a sentence is not in itself a finding about the gene and the disease.
diabetes (continued). "In animal models of diabetes, histidine supplementation could reduce the levels of IL-6, TNF-α and CRP." (PMID 27409634, 2016). "Thus, PGE2-EP4 has similar effects in vitro and in vivo on IL-6 and TNF-α in diabetic mice, and the effects of diabetes on Il6 and Tnfa are dependent on myeloid cell EP4." (PMID 27351842, 2016). "There are no studies in the literature investigating the expression of proinflammatory(IFN-γ, TNF-α, IL-17A) and anti-inflammatory (IL-4, IL-10) cytokines in serum ofpatients with type 2 diabetes mellitus submitted to duodenojejunal bypass surgery withileal interposition without gastric resection." (PMID 26734798, 2015). "However, RT-PCR analysis of locally wounded skin tissues revealed that diabetes down-regulates the RNA expression of both TNF-α and MIF genes in comparison to the control samples but that CMP was found to restore RNA expression significantly." (PMID 26498022, 2015). "The role of inflammatory cytokines TNF-α and IL-1β in the damage of retinal endothelial cells during the early and late stages of diabetic retinopathy in a rat model with streptozotocin-induced diabetes has been investigated." (PMID 26262605, 2015). "To understand the mechanism underlying the effects of ASCs on CAIA, we examined the serum levels of five cytokines (IL-15, IL-1α, IL-6, IL-7, and TNFα), five diabetes-related hormones (resistin, GIP, GLP-1, ghrelin, and leptin), and adiponectin using multiplex immunoassays." (PMID 26210906, 2015). "Thus prolonged elevated levels of IL-6 and TNF-α can interfere with carbohydrate metabolism which can lead to glucose intolerance and diabetes mellitus." (PMID 25806806, 2015). "However, RT-PCR analysis of locally wounded skin tissues revealed that diabetes down-regulated the RNA expression of TNF-α, while CMP was found to significantly restore its RNA expression." (PMID 26498022, 2015). "Therefore, anti-TNF-α blockers such as ETN are expected to suppress aggravation of brain injury in diabetes." (PMID 26665003, 2015). "Our results in accordance with in vitro studies showed that both ascorbic acid and alpha-tocopherol could decrease serum level of TNF-α in patients with diabetes mellitus type 2." (PMID 26693410, 2015). "Diabetes can also induce expression of TNF-α, MMP-2, and MMP-9 in the retina which may enhance apoptosis in the tissue and contribute to the pathogenesis of diabetic retinopathy." (PMID 25821481, 2015). "ELISA analysis of serum TNF-α protein levels showed that it was elevated by diabetes." (PMID 26498022, 2015). "It has been recently reported that uncontrolled diabetes significantly enhanced TNF-α level." (PMID 25114929, 2014). "The subgroup analyses showed that hypertension and diabetes may have some relevance with the gene expression of IL-1β and TNF-α." (PMID 25551602, 2014). "In congruence with the decreased β-catenin levels in the retina of the diabetic KO mice, retinal VEGF and TNF-α levels were also significantly lower in the retina of the diabetic KO mice, compared with that in the WT mice with the same duration of diabetes and similar levels of hyperglycemia." (PMID 25271989, 2014). "Two months of diabetes significantly increased retinal TNFα levels." (PMID 24695399, 2014). "However, cells from donors with diabetes showed a striking 3-fold greater effect of TNF than control cells (black bars)." (PMID 24466329, 2014). "Despite extensive research, there are still unexplored areas and unanswered questions regarding the role of inflammation in the pathogenesis of renal damage in diabetes mellitus and furthermore the implication of TNF-α in the initiation of inflammatory cascade." (PMID 25587544, 2014). "In the pathogenesis of diabetes mellitus, proinflammatory cytokines such as tumor necrosis factor-α (TNF-α) and interleukin-6 (IL-6) could be produced by immunocytes (like macrophages) and adipocytes." (PMID 24669227, 2014).
diabetes (continued). "In two never studies, treatment with TNF-α inhibitors showed an improvement in blood glucose and a lower risk of diabetes." (PMID 24692847, 2014). "Excess TNF-α levels in inflammatory diseases including diabetes may contribute to osteopenia by inhibiting the proliferation of pluripotent cells by down-regulating lysyl oxidase." (PMID 24971753, 2014). "TNF-α in periodontal tissues, the production of which is induced by plaque bacteria including P. gingivlis and is increased by diabetes, may lead to persistent infection of P. ginigvalis and prolongation of immune responses in periodontal tissues." (PMID 25179218, 2014). "In addition, NR4A1 expression was shown to significantly correlate with the levels of the inflammatory cytokines, TNF-α and IL-6, as well as the diabetes-related parameters, FIN, FBG, HOMA-IR and FFA." (PMID 25289075, 2014). "Earlier, the role of inflammatory cytokine TNF-α in the apoptotic cell death of retinal endothelial cells during early and late stages of diabetic retinopathy in a rat model of streptozotocin-induced diabetes has been investigated." (PMID 23365614, 2013). "Understanding the activity of TNF-α on the retinal endothelium may offer a novel way to slow retinal damage induced by diabetes." (PMID 23592916, 2013). "In the context of immunotherapy of diabetes, TNF-alpha is a rational target not only because is cytotoxic to pancreatic beta cells, but also because some studies have found high levels of this cytokine compared to controls in subjects in whom had been recently diagnosed with T1DM." (PMID 24124913, 2013). "Elevated tumor necrosis factor-alpha (TNF-α) levels and hyperglycemia are involved in diabetes associated endothelial dysfunction and may cause premature atherosclerosis." (PMID 23785355, 2013). "The two-day blister model may be well suited for examining impaired wound healing in diabetes, where TNFα dysregulation has been shown to drive inflammatory and apoptotic processes, as well as impairing signalling in wounds." (PMID 23738227, 2013). "However, in oxidative stress-related diseases, such as diabetes or atherosclerosis, MNs are permanently activated and produce high levels of ROS and the proinflammatory cytokines IL-6, IL-1, and tumor necrosis factor alpha (TNF-α)." (PMID 23533689, 2013). "In the retina, it was shown that diabetes activates induction of proinflammatory mediators such as monocyte chemoattractant protein-1, interleukin-6, intercellular adhesion molecule-1, inducible nitric oxide synthase, matrix metalloproteinase-9, and TNF-alpha." (PMID 24259948, 2013). "Similarly, the gene product known as phosphoprotein enriched in astrocytes 15 kDa/phopsphoprotein enriched in diabetes (PEA-15/PED) is a death effector domain-containing protein that modulates TNF-α-induced apoptosis in astrocytes." (PMID 23533150, 2013). "Diabetes-enhanced and prolonged expression of TNF-α also contributes to impaired healing." (PMID 23484152, 2013). "In the current study, we showed that plasma levels of TNF-alpha and IL-6 were remarkably elevated in diabetic rats at 4 weeks after the establishment of diabetes, and NAC treatment decreased them, indicating that NAC can inhibit the inflammation reaction in diabetes." (PMID 23853776, 2013). "However, BC was positively associated with markers of inflammation in men with CHD (particularly vascular endothelial growth factor) and in men with diabetes (particularly interleukin-1β and tumor necrosis factor-α)." (PMID 22336131, 2012). "Does neutralization of TNF-α confer benefit or intensify T1D related autoimmunity in the therapeutically challenging and apparently clinically predictive model of new onset overt diabetes in NOD mice?" (PMID 22606220, 2012). "Moreover, diabetes-enhanced TNF-α activates FOXO1 in chondrocytes in vivo by enhancing its nuclear localization." (PMID 22454632, 2012).
diabetes (continued). "It is possible that increased TNF-alpha and IL-1beta levels affect the expression of IL-6, considering that we detected an increase in the number of immunostained cells to IL-6 after 9 and 12 months of diabetes induction." (PMID 22611374, 2012). "Insulin resistance syndrome and type 2 diabetes mellitus are considered as an inflammatory state due to increased production of pro-inflammatory cytokines, such as TNFα and IL-6; b) motility impairment has been described in diabetic patients showing delayed duodenum-cecal transit time." (PMID 23166628, 2012). "Thus, WP supplementationduring diabetes significantly restored the levels of TNF-α, IL-1β,IL-6 and IL-10." (PMID 22708778, 2012). "In our paper, the presentation is quite unusual since all nine of our patients who developed low blood glucose readings after treatment with a TNF-α inhibitor did not have an underlying history of diabetes." (PMID 22234148, 2012). "In summary, our data highlight the potential combined use of serum adiponectin and TNF-α R2 for diabetes prediction model construction in the Chinese population, as an attractive alternative to existing methods which warrant further validation in other populations." (PMID 22615828, 2012). "Based on ROC analysis, the combined use of serum adiponectin and TNF-α R2 resulted in a significant enhancement of diabetes prediction by this clinical prediction model, with the enhancement being comparable to that provided by 2-hour plasma glucose, as assessed with a 75 g OGTT." (PMID 22615828, 2012). "Plasma IL-6 and TNF-α levels were increased in the rats with diabetes." (PMID 21912612, 2011). "In the current analysis, rates of serious infection in the control and tocilizumab-treated groups were higher in patients with preexisting pulmonary disease, diabetes, older age, or higher body mass index and in those concomitantly treated with steroids or previously treated with a TNF inhibitor." (PMID 21884601, 2011). "Similarly varying results have been reported for the induction of both Il-1β and TNFα depending on the duration of diabetes." (PMID 21249158, 2011). "In this study, both plasma TNF-α and IL-6 levels were significantly increased in rats with diabetes, which may contribute to the decreased plasma APN level in diabetes." (PMID 21912612, 2011). "The effect of diabetes on the expression of various inflammatory (TNFα, IL-6, IL-1β and IFNγ) and apoptosis markers (caspase-1) was also evaluated in intact retinas from wt, ApoE−/−, TNFα−/− and ApoE−/−/TNFα−/− mice." (PMID 20856927, 2010). "We selected these markers, including IL-6, because increased levels of these inflammatory cytokines (IL-6 and TNF-α), as well as downstream proteins such as C-RP, ferritin and fibrinogen, have been implicated in the inflammatory response seen in COPD and diabetes." (PMID 20659337, 2010). "However, results from studies using the TNFα inhibitor etanercept on diabetic rats or TNF receptor deficient mice, recently provided strong evidence for the role of TNFα as a promoter of retinal dysfunction in diabetes." (PMID 20856927, 2010). "No significant changes were detected in retinas of ApoE or TNFα deficient mice in response to diabetes." (PMID 20856927, 2010). "On the other hand, TNF-α would not be involved in HFD-induced diabetes in MyD88-deficient mice, because TNF-α level was attenuated in MyD88-deficient mice fed with HFD." (PMID 20824098, 2010). "Experimental animal investigations have shown that mRNA expression for TNF-α, a robust marker of inflammation, is increased in the retina early in the course of diabetes, and moreover, inhibition of TNF-α has demonstrated beneficial effects in the prevention of early diabetic retinopathy." (PMID 21042558, 2010). "Diabetes mellitus is characterized by a systemic pro-inflammatory environment, exhibiting enhanced basal and postprandial circulating levels of pro-inflammatory cytokines, including interleukin (IL)-1β, IL-6 and tumor necrosis factor-α (TNF-α)." (PMID 20386708, 2010).
diabetes (continued). "Direct experimental evidence in mice models of diabetes is limited, with a study demonstrating elevation of TNFα mRNA in male C57Bl6 mice 5 months after induction of diabetes by STZ and another study showing activation of caspase-1/IL-1β signaling in retinas of diabetic mice." (PMID 20856927, 2010). "Taken together, the role of TNF in the pathogenesis of diabetes in NOD mice is still controversial." (PMID 20003451, 2009). "Indeed, TNF-α is a pivotal pro-inflammatory cytokine involved in a number of inflammatory and autoimmune diseases, diabetes and cancer." (PMID 19295914, 2009). "Diabetes is also an inflammation-prone condition because hyperglycemia-induced ROS stimulates signal transduction to elaborate inflammatory cytokines, e.g. TNF-alpha, IL-1beta and IL-6, which facilitates inflammation, endothelial dysfunction, coagulation and exacerbated the severity of diabetes." (PMID 19678956, 2009). "TNF-alpha and IL-6 levels remains significantly elevated after adjustment for sex, age, left ventricular ejection function, body mass index, coronary heart disease, smoking, hypertension and diabetes mellitus with linear regression analysis." (PMID 19909503, 2009). "Our study identifies an important role for TNF-α in the pathogenesis of signature diabetic retinopathy pathologies and demonstrates that etanercept can inhibit retinal cell death and long-term complication of diabetes." (PMID 19641635, 2009). "The induction of TNF-α could be attributed to various conditions that operate in the course of diabetes, such as hyperglycemia and oxidative stress, and inflammatory cytokines such as VEGF or interleukins, which activate the transcription factor NF-κB." (PMID 19641635, 2009). "It is interesting to speculate that the early rise in TNF-α expression in diabetes results in activation of NF-κB that in turn upregulates FasL expression in leukocytes." (PMID 19641635, 2009). "Patients with OSAS have elevated plasma levels of TNF-α and IL-6, and such inflammatory cytokines may be responsible for the development of diabetes." (PMID 20066132, 2008). "However, the modulation of diabetes by TNFα is influenced significantly by the timing of administration or of the in vivo expression of TNFα during the disease pathogenesis." (PMID 18380898, 2008). "A relationship between TNF-α and diabetes has been describedin several stages of this disease." (PMID 16864902, 2006). "Clinical application ofspecific agents that suppress production and/or activityof TNF-α may inhibit the development and exacerbationof chronic diabetic complications." (PMID 14630568, 2003). "However, TNF-α’s mechanism of action in patients with diabetes mellitus and periodontitis remains unclear, particularly regarding its relationship with glycolipid metabolism indices before and after periodontal treatment." (PMID 41244040, 2025). "In diabetes-induced renal injury, caffeic acid protects renal function by reducing serum creatinine and blood urea nitrogen and inhibiting the production of inflammatory cytokines (such as IL-1β, IL-18, IL-6, and TNF-α) and the expression of NLRP3 inflammasome." (PMID 40909020, 2025). "Furthermore, the combination of diabetes and HgCl2 for 45 days significantly increased TNF-alpha levels in both the hippocampus and prefrontal cortex compared to normoglycemic rats treated with HgCl2 (P = 0.000 for both) and untreated diabetic rats (P = 0.000 and P = 0.007, respectively)." (PMID 40726602, 2025). "Furthermore, NF-kB (P < 0.01), TNF-α, and IL-6 (P < 0.05)were significantly reduced, indicating that PAItrap3 may alleviate metabolic dysfunction in diabetes by suppressing inflammatory pathways." (PMID 40575785, 2025). "The tear levels of IL-1RA, IL-8, and TNF-α could reflect diabetes and its progression in severity." (PMID 40864768, 2025).
diabetes (continued). "The intersection between periodontitis, T2DM and COVID-19 disease, occurs when during diabetes mellitus, there is an increase in blood glucose levels (hyperglycemia) and together with the viral infection, an exacerbated inflammatory response is triggered, increasing the production of TNF-α." (PMID 40406515, 2025). "The results showed that the levels of IL‐1β and TNF‐α in the serum samples obtained from the experimental groups increased in the diabetes group, and there was a significant decrease in both the 18β group and the silver nanoparticle‐loaded 18β group as compared to the diabetes group." (PMID 41280745, 2025). "Several studies on diabetes patients treated with conventional periodontal therapy have confirmed a positive effect on local fibroblast proliferation, together with significant reductions in serum levels of inflammatory mediators (e.g., IL-6, TNF-α), and decreased HbA1c." (PMID 40724728, 2025). "Beyond its local periodontal effects, SDD may also reduce systemic inflammatory mediators such as C-reactive protein (CRP), interleukin-6 (IL-6), and tumor necrosis factor-alpha (TNF-α), particularly in systemically vulnerable populations like individuals with diabetes or cardiovascular disease." (PMID 41465800, 2025). "Supporting this protective role, Treg depletion increased IFN-γ and TNF-α expression, promoting monocyte and neutrophil infiltration and exacerbating liver inflammation, suggesting that Tregs may help prevent the progression of liver fibrosis in diabetes." (PMID 40362271, 2025). "Indeed, VitD supplementation reduces the high-sensitivity C-reactive protein (hs-CRP) in patients with diabetes, psychiatric disorders, polycystic ovary syndrome, and advanced kidney disease, and reduces the tumor necrosis factor-α (TNF-α) in patients with diabetes." (PMID 38542817, 2024). "HA also has anti-inflammatory properties, as it can modulate inflammatory processes by inhibiting pro-inflammatory cytokines (IL-1, IL-6, and TNF-α), which may help control the exacerbated inflammatory response seen in periodontitis among patients with diabetes." (PMID 39595081, 2024). "The activation of NF-κB leads to the transcription of pro-inflammatory cytokines, such as tumor necrosis factor-α (TNF-α), interleukin-6 (IL-6), and interleukin-1β (IL-1β), which in turn can further activate NF-κB, intensifying the inflammatory response and hastening the progression of diabetes." (PMID 38671942, 2024). "Further, stimulation of skin cultures with TNF and IL-1β, but not with diabetes-associated factors like insulin and glucose, stimulate S100A8 and A9 expression in the skin, supporting the previous notion of an inflammatory-driven pathological overexpression of S100A8 and A9." (PMID 39337466, 2024). "Thus, the use of TNF-α inhibitors in the treatment of diabetes appears promising." (PMID 38776022, 2024). "Importantly, IL-1 beta and TNF-alpha expression are positive in diabetics, which might explain the increased inflammatory process in diabetes." (PMID 39201678, 2024). "However, since chronicity is an essential factor in the effect of autoimmunity on the course and complications of diabetes and animal studies have shown that NSAIDs only show anti-TNF-like TNF blockade when used in high doses, we excluded acute exacerbation treatments." (PMID 38842591, 2024). "Our study has confirmed the results of other researchers that administration of CoQ10 in rats led to reduced serum TNF-α levels, which may have been attributed to CoQ10’s declining effects on resistin levels which are generally heightened in patients with diabetes." (PMID 38227584, 2024). "According to theories, diabetes mellitus raises the risk of periodontitis through nonenzymatic pathways that result in advanced glycation end products, such as tumor necrosis factor and IL-1, hindering the activity of proinflammatory cytokines and elevating toll-like receptor expression." (PMID 39583447, 2024).